PPP6R3 (protein phosphatase 6 regulatory subunit 3)
Description:
Regulatory subunit of protein phosphatase 6 (PP6). May function as a scaffolding PP6 subunit. May have an important role in maintaining immune self-tolerance.
Synonyms: C11orf23; KIAA1558; PP6R3; SAPL; SAPS3; SAPLa; DKFZp781E2374; DKFZp781O2362; DKFZp781E17107; SAP190; FLJ11058; FLJ43065; MGC125711; MGC125712
Tractability: Antibody: its Gene Ontology location is reachable by antibodies, with high confidence; the Human Protein Atlas places it where antibodies can reach. PROTAC: ubiquitination databases record sites on it; its protein half-life has been measured.
Target class: Protein phosphatase regulatory subunit; Phosphatase; Enzyme; Protein Phosphatase
Gene: Protein-coding gene on chromosome 11 (68,460,475 to 68,615,343, forward strand). Ensembl gene ENSG00000110075.
Subcellular location: Cytoplasm; Nucleus
Subcellular location (Human Protein Atlas): Cytosol; Nucleoplasm; Plasma membrane
Pathways (Reactome):
Cell Cycle: Telomere Extension By Telomerase
Vesicle-mediated transport: COPII-mediated vesicle transport
Gene Ontology:
Molecular function: protein binding; protein phosphatase regulator activity; protein phosphatase binding
Biological process: regulation of signal transduction
Cellular component: cytosol; nucleoplasm; plasma membrane; nucleus; cytoplasm
Genetic constraint (gnomAD): Loss-of-function variants: 27 observed, 77.41 expected, observed/expected ratio (o/e) 0.35, 90% interval 0.26 to 0.48. The upper end of that interval is the gene's LOEUF score, 0.48, which puts it in group 2 of 6, group 1 being the genes least tolerant of losing a copy. Missense variants: 760 observed, 962.52 expected, observed/expected ratio (o/e) 0.79, 90% interval 0.74 to 0.84. Synonymous variants: 332 observed, 347.4 expected, observed/expected ratio (o/e) 0.96, 90% interval 0.87 to 1.05.
Homologues: Orthologues: chimpanzee PPP6R3 (99% identical), macaque PPP6R3 (99% identical), guinea pig PPP6R3 (97% identical), mouse Ppp6r3 (96% identical), rat Ppp6r3 (96% identical), dog PPP6R3 (95% identical), rabbit PPP6R3 (94% identical), pig PPP6R3 (88% identical), tropical clawed frog ppp6r3 (80% identical), zebrafish ppp6r3 (68% identical), Drosophila melanogaster fmt (27% identical), Caenorhabditis elegans saps-1 (19% identical). Paralogues in human: PPP6R2 (48% identical), PPP6R1 (47% identical).
Diseases named in the same sentence as PPP6R3 in open-access papers:
PPP6R3 is named in the same sentence as 43 diseases in open-access papers, as found by Europe PMC text mining. Sharing a sentence is not in itself a finding about the gene and the disease. The quoted sentences say what the papers report.
Sepsis (9 papers, 2017 to 2024). Sepsis is defined as life-threatening organ dysfunction caused by a dysregulated host response to infection. "We also put forward PPP6R3, TAX1BP1, and more highly expressed ADRBK1 as new reference genes in SIRS and sepsis NK cells." (PMID 31075840, 2019). "In four of them, the mean abundance was again higher in sepsis than in SIRS, namely, PPP6R3 (1.7-fold), TAX1BP1 (1.5-fold), DNAJA2 (1.8-fold), and ADRBK1 (1.4-fold)." (PMID 31075840, 2019). "This analysis yielded highly similar expression levels for four of our five candidate reference genes in SIRS and sepsis NK cells, namely, AKIRIN1, PPP6R3, TAX1BP1, and ADRBK1." (PMID 31075840, 2019).
nodular fasciitis (2 papers, 2024 to 2026). A self-limiting, rapidly growing, non-encapsulated benign neoplasm that arises from the soft tissues. "In the literature there are two cases reported with a PPP6R3::USP6 fusion and typical morphology of a nodular fasciitis but with a malignant transformation." (PMID 37951844, 2024).
myeloma (1 paper, 2013). "However, a break point has been reported in the PPP6R3 gene when analysing samples from primary myeloma patients." (PMID 24084050, 2013).
non-Hodgkin lymphoma (1 paper, 2023). Distinct from Hodgkin lymphoma both morphologically and biologically, non-Hodgkin lymphoma (NHL) is characterized by the absence of Reed-Sternberg cells, can occur at any age, and usually presents as a localized or generalized lymphadenopathy associated with fever and weight loss. "The PPP6R3 gene was recently included in a 95-gene blood transcriptome signature that represents a link between C. burnetii, the agent that causes Q fever, and non-Hodgkin lymphoma." (PMID 37345090, 2023).
type 1 diabetes (1 paper, 2023). "Interestingly, PPP6R3, the gene that encodes SAPS3, is located on the type 1 diabetes susceptibility locus, IDDM4, on chromosome 11q1334." (PMID 36914647, 2023).
cancer (4 papers, 2021 to 2024). A tumor composed of atypical neoplastic, often pleomorphic cells that invade other tissues. "PPP6R3 is a regulatory subunit of protein phosphatase 6 and has been implicated in several cancers." (PMID 36416764, 2022).
metabolic disorders (1 paper, 2024). "Serine/threonine–protein phosphatase 6 regulatory subunit 3 (SAPS3) is a negative regulator of AMPK, and when metabolic disorders occur, SAPS3 is inhibited, leading to AMPK phosphorylation." (PMID 38612356, 2024).
PPP6R3 also shares sentences with these, for which no sentence is quoted: COVID-19 (6 papers); acute kidney injury (2); arterial hypertension (2); asthma (2); cardiac arrest (2); chronic kidney disease (2); diabetes (2); immune deficiency (2); morbid obesity (2); neoplasia (2); Obesity (2); breast carcinoma (1); cardiac disease (1); cardiovascular diseases (1); cerebral malaria (1); colorectal cancer (1); colorectal tumors (1); dementia (1); Hepatic steatosis (1); hospital-acquired infection (1); hypertension (1); Hyponatremia (1); infection (1); Insulin resistance (1); Kidney Disease (1); liver fibrosis (1); metabolic syndrome (1); Multiple Organ Failure (1); neuromuscular disease (1); ovarian carcinoma (1).
A further 6 diseases each share a sentence with PPP6R3 in 1 paper.